CSNK1D (casein kinase 1 delta)
Diseases named in the same sentence as CSNK1D in open-access papers (continued):
Sharing a sentence is not in itself a finding about the gene and the disease.
cancer (continued). "Next, we evaluated the clinical importance of CSNK1D across human cancers using the TCGA database." (PMID 35880088, 2022). "Accordingly, compound 1g was found to inhibit TRKA (neurotrophic tyrosine receptor kinase 1, NTRK1), DYRK1A/1B (dual specificity tyrosine-phosphorylation-regulated kinase 1A and 1B), and CK1δ (casein kinase 1 delta, CSNK1D) kinases, reportedly associated with overexpression in cancer cells." (PMID 34959689, 2021). "However, whether SB-203580 can exert anti-cancer effects by inhibiting CSNK1D remains unclear." (PMID 41353440, 2025). "To gain insight into the role of CSNK1D in HNSCC progression, we measured CSNK1D expression in normal, atypical hyperplasia or cancer tissues of human and 4NQO-induced HNSCC mice via IHC analysis." (PMID 41353440, 2025). "Our results showed a positive correlation between CSNK1D and MSI in most cancers, while it was negatively correlated in READ, UCEC, and COAD." (PMID 37688771, 2023). "Moreover, we performed univariate Cox regression analysis to investigate the correlation between CSNK1D expression and disease-free survival (DFS), disease-specific survival (DSS), and progression-free survival (PFS) in the 33 types of cancer." (PMID 37688771, 2023). "Furthermore, we demonstrate a requirement of CSNK1D for GLI-dependent TIC properties in vitro and in vivo, and introduce a novel CSNK1D inhibitor with therapeutic activity against GLI-driven cancer cells." (PMID 34439381, 2021). "In addition, the copy number variations investigation revealed that RORC and CSNK1D genes showed widespread copy number amplification across various cancer types whereas almost no CNV was detected in THCA, KIRC, and KIRP." (PMID 36895015, 2023). "Additionally, CSNK1D showed a positive correlation with TNFRSF25 and CD276 in most cancers." (PMID 37688771, 2023). "Furthermore, our analysis of the estimate score demonstrated a negative correlation with CSNK1D expression in nearly all cancer types, except for DLBC and LAML (P < 0.05)." (PMID 37688771, 2023). "Here, we identify casein kinase 1 delta (CSNK1D) as positive regulator of oncogenic GLI function and show that pharmacological as well as genetic targeting of CSNK1D is sufficient to abrogate HH—GLI signaling in both SMOi-sensitive and SMOi-resistant cancer cells driven by oncogenic GLI." (PMID 34439381, 2021). "Targeting CSNK1D with compounds such as SR-3029 and CK1D008 may, therefore, be a promising future strategy to treat cancer patients with acquired or a priori resistance to SMOi, and to hopefully reduce severe side effects known to be caused by established anti-SMO drugs." (PMID 34439381, 2021). "Genetic and pharmacological inhibition of CSNK1D activity leads to suppression of oncogenic HH—GLI signaling, even in cancer cells in which already approved HH inhibitors are no longer effective due to resistance mechanisms." (PMID 34439381, 2021). "Interestingly, we observed a negative correlation between CSNK1D and HTRA12 in almost all types of cancers." (PMID 37688771, 2023).
tumor (20 papers, 2007 to 2026). "Significant associations were found between CSNK1D expression levels and immune cell infiltrations, immune checkpoint inhibitors, tumor mutation burden, and microsatellite instability across multiple malignancies." (PMID 37688771, 2023). "High expression of CSNK1D was significantly associated with tumor size, tumor differentiation, microvascular invasion, TNM stage, metastasis and recurrence." (PMID 36460966, 2022). "Additionally, the CSNK1D gene is implicated in the formation of resistance of tumor cells to anticancer drugs." (PMID 37688771, 2023). "Though the change in CSNK1D expression had no marked effects on the weight of mice, while CSNK1D deficit reduced tumor growth, and CSNK1D overexpression enhanced the growth." (PMID 41353440, 2025). "We observed that CSNK1D was predominantly localized in the cytoplasm of tumor cells, with limited nuclear distribution." (PMID 41353440, 2025). "We also performed the CCK8 assay, cloning experiments and 3D tumor sphere formation assay to elute the effects of CSNK1D on the proliferation." (PMID 41353440, 2025). "Our analysis validated that CSNK1D functions as a positive regulator of tumor growth, providing a novel and comprehensive demonstration of the involved mechanism." (PMID 41353440, 2025). "To further verify the inhibitory effect of SB-20358 on CSNK1D, we constructed the subcutaneous tumor model by injecting 5 × 105 of HN4 cells into the nude mice." (PMID 41353440, 2025). "CSNK1D expression levels were upregulated in tumor tissues and the up-regulation was positively correlated with poor survival in patients with HNSCC." (PMID 41353440, 2025). "Key genes identified in this subtype included SLBP, MBD1, MINK1, DPH1, and CSNK1D, which are noted in existing literature for their roles in tumor malignancy and progression, thereby reinforcing the reliability of the ac4C score." (PMID 39648231, 2024). "Studies have shown that CSNK1D is essential in tumor cell proliferation, metastasis, angiogenesis, and drug resistance." (PMID 37688771, 2023). "The tumor-initiating role of CSNK1D is further supported by our findings that pharmacological inhibition of CSNK1D abrogates the tumor initiation and in vivo engraftment capacity of GLI-dependent PANC1 cells." (PMID 34439381, 2021). "In keeping with previous observations, these results confirmed the effect of CSNK1D inhibition on tumor growth in vivo." (PMID 30112110, 2018). "The involvement of CSNK1D in matrigel invasion was further studied using a three-dimensional tumor spheroid invasion assay." (PMID 30112110, 2018). "CSNK1D is also involved in multiple pathological processes, including neurologic diseases and disorders, mediating drug addiction, metabolic diseases, tumorigenesis, and tumor progression." (PMID 41353440, 2025). "Furthermore, the transwell and 3D tumor sphere formation assay results indicated reduced invasion ability in the si-CSNK1D group compared with the control group, while CSNK1D overexpression facilitated the invasion of HNSCC cells in the OE-CSNK1D group." (PMID 41353440, 2025). "Furthermore, we have uncovered a correlation between CSNK1D expression and immune cell infiltration in the tumor microenvironment, suggesting its potential role in regulating tumor immunity." (PMID 37688771, 2023). "In conclusion, this study suggests that CSNK1D may serve as a biomarker for tumor prognosis and immunotherapy." (PMID 37688771, 2023). "Furthermore, a correlation between CSNK1D expression and immune cell infiltration in the tumor microenvironment has been uncovered, suggesting its potential role in regulating tumor immunity." (PMID 37688771, 2023). "Furthermore, CSNK1D can also regulate tumor cell metabolism, including glucose and lipid metabolism, affecting tumor cell growth and survival." (PMID 37688771, 2023). "CSNK1D may be involved in modulating the tumor microenvironment, which is known to be critical in tumor onset, advancement, and metastasis." (PMID 37688771, 2023).
tumor (continued). "In vivo, exogenous CSNK1D has been shown to enhance tumor growth and metastasis." (PMID 36460966, 2022). "The xenograft tumor derived from CSNK1D-overexpressing cells had a larger volume than the NC group." (PMID 36460966, 2022). "For this, we examined the role of CSNK1D in MDA-MB-231 tumor cell migration and invasion." (PMID 30112110, 2018). "However, the expression of CSNK1D in KICH tumor tissues is notably reduced." (PMID 37688771, 2023). "Immunoblotting analyses showed that the CSNK1D expression levels were correlated with the levels of E-cadherin, N-cadherin, Vimentin, BCL2, and Bax in the tumor tissues of nude mice." (PMID 41353440, 2025). "In this study, the circadian rhythm gene CSNK1D expression level was significantly correlated with clinical parameters of HCC patients, including tumor stage, differentiation, and survival status." (PMID 36460966, 2022). "According to the observation in TCGA, CSNK1D was highly expressed in multiple tumors, in which LIHC had the most significant fold change between tumor and normal tissues." (PMID 36460966, 2022). "We provide evidence that inhibition of CSNK1D interferes with oncogenic HH signaling in both SMO inhibitor-sensitive and -resistant tumor settings." (PMID 34439381, 2021). "By integrating bulk and single-cell transcriptomic data, we identify subtype-specific roles of key circadian regulators-including ALAS1, NONO, and CSNK1D-in shaping tumor metabolism, proliferation, stromal remodeling, and immune suppression." (PMID 41898292, 2026). "Expression of CSNK1D was increased in tumor CNV amplification samples relative to nonapplication samples and normal tissues, which corresponds with the CNV profile of the CCGs." (PMID 36439444, 2022). "Moreover, our results showed that ACTG1, CSNK1D, PPP1CC, and BIRC5 expression was negatively correlated with miR-497-5p expression in HCC tumor biopsies (n = 364, r = −0.32, -0.29, -0.24, and -0.33, respectively, p < 0.001)." (PMID 33816607, 2021). "To further verify whether CSNK1D affected tumor development through the HH pathway, we applied the agonists of the HH pathway (SAGs) into the CSNK1D-knockdown CAL27 or HN4 cells, and the HH pathway inhibitor (SANT1) into CSNK1D-overexpressed cells." (PMID 41353440, 2025).
infection (2 papers, 2018 to 2025). The state of being infected such as from the introduction of a foreign agent such as serum, vaccine, antigenic substance or organism. "This module of 127 genes (including per3, csnk1d, ciart) was predominantly enriched for GO terms related to circadian functions (e.g. circadian regulation of gene expression), indicating significant disruption of molecular clock expression due to infection." (PMID 30285628, 2018).
CSNK1D also shares sentences with these, for which no sentence is quoted: Alzheimer disease (2 papers); amyotrophic lateral sclerosis (1); Angelman syndrome (1); cholangiocarcinoma (1); clear cell renal cell carcinoma (1); colon cancer (1); endometrial cancer (1); lung squamous cell carcinoma (1); mucopolysaccharidosis type 2 (1); multiple myeloma (1); myotonic dystrophy (1); narcolepsy (1); ovarian tumours (1); pancreatic cancer (1); Parkinson disease (1); sarcoma (1); Sepsis (1); substance dependence (1).